RBFOX1 (RNA binding fox-1 homolog 1)
Diseases named in the same sentence as RBFOX1 in open-access papers (continued):
Sharing a sentence is not in itself a finding about the gene and the disease.
schizophrenia (continued). "To investigate the functional impact of Rbfox1-Vamp1 alterations in schizophrenia, we simulated the effect of lower GABA release probability from PVIs on gamma power in a computational model network of pyramidal neurons and PVIs." (PMID 37398467, 2023). "The mean levels of cytoplasmic Rbfox1 immunoreactivity (F1,9=5.2, P = 0.048) and the mean density of PV mRNA grains (F1,9=4.4, P = 0.065) were each 14% lower in PVIs in schizophrenia, respectively." (PMID 37398467, 2023). "To validate that this approach can reliably sample affected PVIs in fresh-frozen PFC sections of schizophrenia, we selected the 10 subject pairs with the largest difference in cytoplasmic Rbfox1 protein levels in fixed PFC sections." (PMID 37398467, 2023). "Mean levels of cytoplasmic Rbfox1 immunoreactivity were significantly (F1,19=17.2, p < 0.001) 29% lower in PVIs from individuals with schizophrenia relative to unaffected comparison subjects." (PMID 37398467, 2023). "We then investigated the functional consequence of altered Rbfox1-Vamp1 pathway in schizophrenia by simulating how changing the release probability of inhibitory drive from PVIs affects gamma power in a computational model network." (PMID 37398467, 2023). "In this study, we investigated if the Rbfox1-Vamp1 pathway is altered in PVIs in PFC of individuals with schizophrenia by utilizing a novel strategy that combines multi-label in situ hybridization and immunohistochemistry." (PMID 37398467, 2023). "The CAMK1D, GABRB3, and RBFOX1 genes have been suggested to contribute to schizophrenia physiopathology." (PMID 30034349, 2018). "Since neurodevelopmental disorders such as ASD and schizophrenia are thought to be “synapse” diseases, these results suggest a crucial role of Rbfox1-iso2 in not only the developing but also the adult brain." (PMID 26500751, 2015). "Gene abnormalities in RBFOX1, encoding an mRNA-splicing factor, have been shown to cause ASD and other neurodevelopmental and psychiatric disorders such as ID, ADHD, and schizophrenia." (PMID 26500751, 2015). "In addition to lower levels of cytoplasmic Rbfox1, the mean levels of nuclear Rbfox1 (F1,19=19.9, p < 0.001) and total Rbfox1 (F1,19=19.9, p < 0.001) immunoreactivities were also lower in PVIs in schizophrenia subjects." (PMID 37398467, 2023). "However, we found similar reductions in the levels of total and both Rbfox1 isoforms in PVIs in schizophrenia, as well as lower levels of PV which is expressed in an activity-dependent fashion." (PMID 37398467, 2023). "Finally, the levels of Vamp1 mRNA, a major target transcript of cytoplasmic Rbfox1, were lower in PVIs in schizophrenia and were predicted by lower cytoplasmic Rbfox1 protein levels across these neurons." (PMID 37398467, 2023). "Together, these findings demonstrate that Vamp1 mRNA levels are lower in PVIs in schizophrenia and suggest that this alteration could be due to deficits in cytoplasmic Rbfox1 levels in these neurons." (PMID 37398467, 2023). "Together, these findings support the hypothesis that the nature of Rbfox1 pathway alterations in schizophrenia includes lower levels of cytoplasmic Rbfox1 protein isoform and of its target Vamp1 mRNA in prefrontal PVIs." (PMID 37398467, 2023). "To investigate if cytoplasmic Rbfox1 isoform levels are altered in PVIs in schizophrenia, we first examined whether Rbfox1 and its isoforms are enriched in these neurons in human PFC." (PMID 37398467, 2023). "Cytoplasmic Rbfox1 protein levels in PVIs are lower in schizophrenia." (PMID 37398467, 2023). "Next, we investigated whether lower cytoplasmic Rbfox1 levels in PVIs in schizophrenia might be due to methodological confounds or diagnosis-associated co-occurring factors." (PMID 37398467, 2023). "Finally, we investigated the relationship between the levels of cytoplasmic Rbfox1 protein and Vamp1 mRNA in PVIs in schizophrenia." (PMID 37398467, 2023).
schizophrenia (continued). "Moreover, the levels of cytoplasmic and nuclear Rbfox1 isoforms were significantly positively correlated across both unaffected comparison and schizophrenia subjects and these correlations were also evident across individual PVIs." (PMID 37398467, 2023). "To investigate if lower cytoplasmic Rbfox1 protein levels predict lower Vamp1 mRNA levels in PVIs in schizophrenia, we first explored whether Vamp1 is highly expressed in these neurons in human PFC." (PMID 37398467, 2023). "At the gene level, RBFOX1 was found to be associated with several psychiatric conditions, obtaining again gene-wide significance for MDD (p = 8.62e-17), RT (p = 5.6e-12), and CD-MA (p = 1.2e-10), but also for schizophrenia (SCZ; p = 7.2e-08)." (PMID 35948661, 2022). "Furthermore, the levels of cytoplasmic Rbfox1 immunoreactivity were significantly positively correlated with the density of Vamp mRNA grains across individual PVIs in both unaffected comparison and schizophrenia subjects." (PMID 37398467, 2023). "However, direct evidence for altered Rbfox1 expression in PVIs in schizophrenia, and dysregulated regulation of its target transcripts involved in impaired cortical inhibition, remain unknown." (PMID 37398467, 2023). "Together, these findings support our hypothesis that schizophrenia is associated with lower cytoplasmic Rbfox1 levels in PVIs and suggest that this alteration is not due to methodological confounds or diagnosis-associated co-occurring factors." (PMID 37398467, 2023). "In concert, these findings support the regulatory role of cytoplasmic Rbfox1 on Vamp1 levels in human PFC and suggest that lower cytoplasmic Rbfox1 protein levels contribute to lower Vamp1 mRNA levels in PVIs in schizophrenia." (PMID 37398467, 2023). "Therefore, examining the levels of cytoplasmic Rbfox1 isoform and Vamp1 mRNA in PVIs could provide important insights into molecular mechanisms underlying impaired cortical inhibition and deficient PFC gamma oscillations in schizophrenia." (PMID 37398467, 2023). "Consistently, RBFOX1 expression appeared decreased in post-mortem frontal and temporal cortices of individuals with ASD and prefrontal cortex of individuals with schizophrenia." (PMID 35948661, 2022). "Since RBFOX1 gene abnormalities have also been found in other neurodevelopmental and psychiatric disorders including ID, ADHD and schizophrenia, this gene product is supposed to have an essential role in neuronal function and corticogenesis." (PMID 27481563, 2016). "Additionally, NPAS3 has been linked to schizophrenia and bipolar disorder, CLSTN2 has been associated with memory performance and with Alzheimer’s disease, and RBFOX1 (A2BP1) has been very recently discovered as a splicing regulator of neuronal excitation and calcium homeostasis in the brain." (PMID 22888310, 2012). "To test this hypothesis, we applied a novel technical strategy that combines multi-label in situ hybridization and immunohistochemistry in postmortem human brain to quantify the levels of cytoplasmic Rbfox1 isoform and Vamp1 mRNA in the same PVIs in the PFC of individuals with schizophrenia." (PMID 37398467, 2023). "Thus, deficits in multiple molecular mechanisms, including Rbfox1-Vamp1 alterations, could result in reduced GABA release probability that contributes to impaired generation of PFC gamma oscillations in schizophrenia." (PMID 37398467, 2023). "In the PFC of 20 matched pairs of schizophrenia and comparison subjects, cytoplasmic Rbfox1 protein levels were significantly lower in PVIs in schizophrenia and this deficit was not attributable to potential methodological confounds or schizophrenia-associated co-occurring factors." (PMID 37398467, 2023). "RBFOX1 gene has been recently shown to serve as a ‘hub’ in autism spectrum disorder (ASD) transcriptome networks and in neurodevelopmental and psychiatric disorder including intellectual disability (ID), attention deficit hyperactivity disorder (ADHD) and schizophrenia." (PMID 33317634, 2020).
schizophrenia (continued). "As multiple target transcripts of Rbfox1 have been shown to regulate synaptic transmission, future studies investigating alterations in additional Rbfox1 target transcripts and their involvement in PFC dysfunction may further validate the role of Rbfox1 in schizophrenia." (PMID 37398467, 2023). "Thus, the effect of antipsychotics is unlikely to account for lower Rbfox1 levels in schizophrenia." (PMID 37398467, 2023). "However, the nature of alterations in Rbfox1 protein isoforms and their target transcripts, and their potential impact on PFC dysfunction, had not been investigated in schizophrenia." (PMID 37398467, 2023).
autism spectrum disorder (22 papers, 2009 to 2025). A spectrum of developmental disorders that includes autism, and Asperger syndrome. "For instance, we report pleiotropy for the RBFOX1 gene which is known to be mainly expressed in the brain and to have a causal role in autism spectrum disorder." (PMID 34326310, 2021). "CSMD1 is an important regulator of complement activation and inflammation, while RBFOX1 encodes for an mRNA-splicing factor linked to autism spectrum disorders." (PMID 34868193, 2021). "Gene abnormalities in RBFOX1, encoding an mRNA-splicing factor, have been shown to cause autism spectrum disorder and other neurodevelopmental disorders." (PMID 27481563, 2016). "The homologous gene RBFOX1 has been implicated in several neurodevelopmental disorders, including Rolandic Epilepsy and Autism Spectrum Disorder, and is a downstream target of FOXP2, a transcription factor implicated in monogenic speech and language disorders." (PMID 25065397, 2014). "In the case of microexons, SRRM4 and RBFOX1 have a critical role in coordinating microexon inclusion through brain development, and changes in the expression of these splicing factors have been linked to misregulation of alternative splicing events in individuals with autism spectrum disorder (ASD)." (PMID 33482885, 2021). "Accumulating evidence strongly suggests a role of RBFOX1 in the etiology of autism spectrum disorder (ASD)." (PMID 27481563, 2016). "Common variation in the gene encoding the neuron-specific RNA splicing factor RNA Binding Fox-1 Homolog 1 (RBFOX1) has been identified as a risk factor for several psychiatric conditions, and rare genetic variants have been found causal for autism spectrum disorder (ASD)." (PMID 35948661, 2022). "In addition, we also selected one gene set from their autism spectrum disorder (ASD) gene list (included for the shared pathophysiology between psychiatric disorders) - targets of RBFOX1 (RNA binding protein, fox-1 homolog 1), since it is a brain- and muscle-specific splicing factor." (PMID 40690510, 2025). "Rare genetic variations, including point mutations and copy number variants, have been reported in RBFOX1 in patients with neurodevelopmental disorders such as autism spectrum disorder (ASD), and RBFOX1 haploinsufficiency results in a syndrome characterised by impaired neurodevelopment." (PMID 38374212, 2024).
heart failure (15 papers, 2014 to 2025). Inability of the heart to pump blood at an adequate rate to meet tissue metabolic requirements. "The genetic deletion of Rbfox1 from cardiomyocytes predisposed hearts to develop heart failure in response to cardiac pressure overload." (PMID 40358188, 2025). "The expression of RBFOX1 is significantly reduced in the failing heart, whereas cardiac deficiency of RBFOX1 results in heart failure in both mouse and zebrafish." (PMID 39045460, 2024). "Downregulation of RBFOX1 (RNA-binding protein, fox-1 homologue) is associated with heart failure in humans and mouse models, and the loss of Rbfox1 exacerbates pressure overload-induced heart failure in mice." (PMID 30051286, 2018). "More importantly, loss of Rbfox1 significantly contributed to the development of cardiac hypertrophy and heart failure in the mouse pressure-overload model and restored Rbfox1 expression was able to prevent pathological hypertrophy." (PMID 29186814, 2017). "The protein that RBFOX1 encodes is a muscle-specific isoform of an RNA splicing regulator and previous study identified that regulation of RNA splicing by RBFOX1 played a crucial role in transcriptome reprogramming during heart failure." (PMID 36539828, 2022). "Their work with mouse models has shown RBFox1 deficiency in the heart promoted pressure overload–induced heart failure, and induction of RBFox1 over-expression in these murine pressure-overload models, substantially attenuated cardiac hypertrophy and pathological manifestations." (PMID 29765130, 2018). "Downregulation of RBFOX1 was associated with heart failure in humans and mice." (PMID 29304022, 2018). "RBFox1 deficiency aggravates pressure overload-induced heart failure in the mice model." (PMID 29304022, 2018). "RBFOX1 expression has been associated with cardiac hypertrophy and heart failure in mice models." (PMID 28346479, 2017). "A role of RBFOX1 in the development of heart failure was recently established, as both murine and human failing hearts showed a reduced expression of RBFOX1." (PMID 40358188, 2025). "Likely, the role of RBFOX1 is not limited to the splicing of MEF2, and it is possible that additional functions of RBFOX1 are crucial to maintain normal cardiac function and provide protection against heart failure." (PMID 40358188, 2025). "Given the importance of Ca2+ homeostasis in cardiac function, we explored a role for RBFOX1 in regulating Ca2+ homeostasis as a contributing factor to heart failure." (PMID 40358188, 2025). "It was recently established that alternative splicing by the RNA-binding protein RBFOX1 is critical to maintain normal cardiac function in zebrafish and to protect the murine heart from pressure overload-induced heart failure." (PMID 40358188, 2025). "Our results render Rbfox1, as well as its validated targets, new candidates for involvement in human cardiomyopathy and heart failure." (PMID 26116573, 2015). "RBFOX1 is a prominent regulator of alternative RNA splicing during heart failure." (PMID 39045460, 2024). "Additionally, RBFOX1 has a well-described role in regulating alternative splicing within cardiomyocytes to mediate contractile changes in heart failure and, thus, is likely playing an incidental role in mitral valve biology." (PMID 35132965, 2022). "Finally, induction of Rbfox1 expression in murine pressure overload models substantially attenuated cardiac hypertrophy and progression to heart failure." (PMID 30051286, 2018). "ASF/SF2 and RBFOX1/2 regulate the splicing of the CaMKIIδ gene and thus expression of δB and δC, but whether changes in splicing occur in and contribute to the development of heart failure or I/R injury remains to be determined." (PMID 24575042, 2014). "Despite its global impact on cardiac mRNA splicing, the RBFOX1-mediated isoform switch (α1 versus α2) of MEF2 genes (MEF2A, MEF2C and MEF2D) appears to be a crucial regulatory circuit contributing to the development of heart failure." (PMID 39045460, 2024).
heart failure (continued). "They, furthermore, point to a critical role for RBFOX1 in protecting the heart from failure and might provide a novel therapeutic target for heart failure." (PMID 40358188, 2025).
Intellectual disability (15 papers, 2012 to 2024). "Several genes related to intellectual disability (Dcaf17, Myst4, Park2, Rbfox1) were found to be hypo-methylated in male pups, and genes (Pfn1, Cntnap1, Drp2) related to normal function of the nervous system were hypo-methylated in female pups from the HMFA group." (PMID 27199632, 2016). "Along with a key role as A2BP1 in spinocerebellar ataxia type-2, the other structural variants and deletions in the RBFOX1 gene increase the risk and development of disorders associated with aggression, generalised epilepsy, ASD, intellectual disability, and cognitive dysfunction in SCZ." (PMID 36833409, 2023).
cardiac hypertrophy (11 papers, 2011 to 2025). "Deficiency in the heart of RBFOX1, being an important player in transcriptome reprogramming in HF, promotes pressure-overload-induced cardiac hypertrophy." (PMID 39273537, 2024). "Stimulating RBfox1 in mice with an inducible expression of RBFox1 was protective against cardiac hypertrophy and the loss of contractile function in response to pressure overload." (PMID 34573439, 2021). "We furthermore showed that the deletion of Rbfox1 drives cardiac hypertrophy and cardiac dysfunction in response to pressure overload stimulation." (PMID 40358188, 2025). "Since it was previously shown that RBFOX1 deletion results in mild cardiac dysfunction in young adult mice, we wanted to assess whether cardiac dysfunction and/or cardiac hypertrophy were already present at a young age." (PMID 40358188, 2025). "This study provides evidence that regulation of RNA splicing by Rbfox1 may play an important role in transcriptome reprogramming, including CACNA1C mRNA, during cardiac hypertrophy that influences the pathogenesis of the disease." (PMID 29186814, 2017).
Obesity (11 papers, 2014 to 2026). Accumulation of substantial excess body fat. "The RBFOX1 gene was selected as an exploratory candidate gene because it encodes an RNA-binding splicing regulator, has been implicated in obesity-related phenotypes, and has been reported in candidate-gene analyses of periodontitis/metabolic traits." (PMID 42278395, 2026). "The involvement of RBFOX1 in obesity development is questionable and warrants further investigation." (PMID 31852448, 2019). "Therefore, it is inconclusive whether RBFOX1 is an obesity gene." (PMID 28346479, 2017). "Our result indicates the RBFOX1 contributes to BP variation independent of obesity, although we are unclear whether RBFOX1 has a pleiotropic effect on both BP and obesity." (PMID 28346479, 2017).
Alzheimer disease (7 papers, 2012 to 2023). A progressive, neurodegenerative disease characterized by loss of function and death of nerve cells in several areas of the brain leading to loss of cognitive function such as memory and language. "RBFOX1 downregulation is more likely to occur in older and female individuals, consistent with the association of Alzheimer’s disease with age and gender." (PMID 29030541, 2017). "Furthermore, Rbfox1 has been implicated in neuroprotective effect of miR-132 against amyloid β-peptide (Aβ) and glutamate excitotoxicity in Alzheimer’s disease." (PMID 34108862, 2021). "We show that downregulation of RBFOX1 leads to destabilization of mRNAs encoding for synaptic transmission proteins, which may contribute to the loss of synaptic function in Alzheimer’s disease." (PMID 29030541, 2017). "Interestingly, two variants associated with low z-insulin in the present study were located on RBFOX1 and SH3RF3, genes that have previously been shown to be related to brain amyloidosis in preclinical Alzheimer’s disease and to late-onset Alzheimer’s disease, respectively." (PMID 37420130, 2023).
bipolar disorder (7 papers, 2009 to 2025). A disorder of the brain that causes unusual shifts in mood, energy, activity levels and the ability to carry out day-to-day tasks. "Moreover, Rbfox1, one of the plasticity genes identified in the enrichment analyses is also linked to risk for ASDs, TRANK1 is a susceptibility gene for bipolar disorder, and RIMS1 was identified in a PTSD TWAS." (PMID 38263132, 2024).